FTO (FTO alpha-ketoglutarate dependent dioxygenase)
Diseases named in the same sentence as FTO in open-access papers (continued):
Sharing a sentence is not in itself a finding about the gene and the disease.
tumor (continued). "Previous studies have demonstrated the role of FTO in cancer cell proliferation, metastasis, apoptosis, regulation of cancer stem cells, regulation of the tumor microenvironment, and drug resistance." (PMID 40243425, 2025). "Tumor growth analysis revealed a significant increase in tumor volume in the FTO‐KO group compared to the NC‐KO group." (PMID 41141648, 2025). "Another study has suggested that FTO works as a tumor suppressor by downregulating SLC7A11 in order to suppress metastasis." (PMID 40243425, 2025). "Recently, FTO-mediated m6A demethylation promotes glycolytic activity in tumor cells, which impedes CD8+ T cell infiltration and effector function." (PMID 40234389, 2025). "Immunohistochemical analyses revealed predominant nuclear localization of FTO and reduced expression in tumor compared to the paired peritumoral tissues." (PMID 40316995, 2025). "Collectively, these findings suggest that the targeted inhibition of METTL3 and FTO, in combination with radiotherapy, enhances the suppression of tumor growth and progression." (PMID 40823093, 2025). "As above, lipid metabolism has emerged as an important target for anti-tumor strategies, and its role in pNENs influenced by FTO remains unexplored." (PMID 39990672, 2025). "Given FTO’s cancer-promoting effects, a variety of FTO inhibitors have been developed, and their therapeutic efficacy has been validated in tumor models." (PMID 41269404, 2025). "Targeting FTO can suppress tumor growth, enhance tumor immunotherapy, and mitigate tumor drug resistance." (PMID 40823087, 2025). "FTO expression was elevated in most tumor samples compared to the corresponding normal adjacent tissues in five paired pNEN samples." (PMID 39990672, 2025). "Subsequently, we performed IHC staining on a tissue microarray comprising tumor tissues (n = 70) and adjacent tissues (n = 70) to determine FTO protein levels." (PMID 39773744, 2025). "Collectively, animal studies indicate that combining FTO inhibition with ibrutinib synergistically reduces tumor growth and metastasis and improves survival, highlighting their potential in cancer treatment." (PMID 41281757, 2025). "By integrating transcriptome data with clinical tissue analysis and functional experiments, we demonstrated that low FTO expression correlated with poor tumor behavior and FTO restoration suppressed tumorigenesis in both cellular and animal models." (PMID 41141648, 2025). "Inhibition of FTO with FB23 significantly reduced tumor progression, particularly when combined with Everolimus." (PMID 41458541, 2025). "IHC analysis revealed that FTO is predominantly localized in both the nucleus and cytoplasm of tumor cells, supporting its multifaceted regulatory role." (PMID 41141648, 2025). "The tumor size underwent a substantial reduction upon FTO overexpression (2259.0 ± 980.4 mm3 versus 438.9 ± 283.1 mm3, P = 0.006)." (PMID 40316995, 2025). "Elevated FTO expression was found to correlate with advanced clinical grade, lymph node metastasis, larger tumor size, and poor survival outcomes." (PMID 39773744, 2025). "In contrast, the FTO‐OE group exhibited a marked reduction in tumor weight compared to the NC‐OE group." (PMID 41141648, 2025). "For instance, FTO-mediated m6A demethylation in tumor cells enhances the expression of transcription factors c-Jun, JunB, and C/EBPβ, which rewires glycolytic metabolism." (PMID 39987091, 2025). "More recently, FTO was shown to play a role in many types of cancer, both with oncogenic and tumor suppressive functions depending on tumor type and/or stage." (PMID 40022434, 2025). "The upregulation of FTO is connected to enhanced tumor proliferation and progression, which is attributed to its capacity to diminish m6A methylation in oncogenes." (PMID 40675967, 2025).
tumor (continued). "This selectivity is likely due to the differential expression of VHL between tumor cells and normal tissues, allowing FP54 to target and degrade FTO more specifically in tumor cells while sparing normal cells." (PMID 40815637, 2025). "In NSCLC, FTO can mediate tumor progression through FTO-mediated autophagy and FAP/integrin/FAK signaling." (PMID 40722726, 2025). "In mouse models of cancer, combining FTO knockdown with ibrutinib markedly suppressed tumor growth, decreased metastasis, and improved survival." (PMID 41281757, 2025). "Previous reports have also demonstrated that FTO was abundantly expressed in the lungs, and its expression patterns differed in the tumor region compared to the surrounding normal tissue region." (PMID 40722726, 2025). "Beyond its function in modulating cancer cell proliferation, metastasis, and CSC self-renewal, FTO also plays a pivotal role in the regulation of the tumor microenvironment (TME) and tumor metabolism." (PMID 39449798, 2024). "This investigation aims to uncover how FTO contributes to the dynamics of tumor growth and spread within these specific malignancies." (PMID 39175477, 2024). "In parallel, R‐2HG, a separate inhibitor of FTO, heightens the responsiveness of tumor cells to therapeutic drugs, leading to tumor cell elimination." (PMID 38706740, 2024). "Interventional therapies targeting FTO can inhibit tumour growth, enhance immune effects, inhibit drug resistance and sensitise chemotherapeutic agents through multiple biological effects." (PMID 39163517, 2024). "Knocking down FTO reduces the glycolytic activity of tumor cells, restoring the functional capabilities of CD8+ T cells and effectively blocking immune escape mechanisms, thereby inhibiting tumor growth." (PMID 39072324, 2024). "The context-dependent role of FTO as oncogenic or tumor-suppressive is complex and requires further investigation of its underlying molecular mechanisms." (PMID 38503745, 2024). "FTO is involved in the regulation of tumor progression by decreasing the abundance of m6A and activating specific signaling pathways, reducing the overall survival rate of patients afflicted with malignant tumors." (PMID 39054967, 2024). "They inhibit FTO demethylase activity by selectively binding to and occupying the catalytic pocket of FTO and demonstrate potent anti-tumor effects and high clinical feasibility in various cancers." (PMID 39473440, 2024). "The authors mentioned that although six studies shown tumor-suppressive function of FTO, but another three studies suggest that FTO is oncogenic protein." (PMID 38075202, 2024). "FTO is reported to induce oxidative stress and apoptosis in OC, leading to suppressed tumor in nude mice." (PMID 38544837, 2024). "Across a broad spectrum of cancer types, FTO is commonly found to be upregulated, serving as a crucial promoter of tumor progression." (PMID 39744011, 2024). "Changes in m6A levels during tumor occurrence and metastasis were shown to be dependent on the regulation of the expression level of demethyltransferase FTO." (PMID 38384328, 2024). "This study primarily concentrates on exploring the expression and functionality of FTO within tumor contexts." (PMID 39449798, 2024). "The tumor volume was significantly larger in the FTO knockout group than in the control group, in line with the growth rate tested via tumor weights." (PMID 38384328, 2024). "FTO has been suggested to function as both an oncogene and a tumor suppressor, depending on the cancer type." (PMID 39300486, 2024). "Decreased FTO level correlated with increased tumor severity and poor overall and cancer-specific survival following nephrectomy, suggesting a tumor-suppressive role of FTO." (PMID 38503745, 2024). "The METTL3 and FTO-related tumor signaling pathways and small molecule targeted drugs have been abundantly reported." (PMID 38711100, 2024).
tumor (continued). "m6A demethylase FTO displays the oncogenic function via reducing the tumor suppressor mRNA level, resulting in cancer cell differentiation and tumor growth." (PMID 38589454, 2024). "Mechanistically, the loss of FTO increases the m6A levels of chloride intracellular channel 4(CLIC4) and ERG2, which are two tumor suppressors in PCa, accelerating their degradation." (PMID 39268470, 2024). "In ccRCC, downregulation of FTO enhanced autophagic flux, leading to inhibition of tumor growth and metastasis in vivo and in vitro." (PMID 38576024, 2024). "For example, several reports indicate that FTO has tumor suppressor activities on CRC invasiveness and metastasis, ovarian cancer stem cell self-renewal, and papillary thyroid cancer." (PMID 39136000, 2024). "Collectively, these results suggest that FTO exerts a tumor-suppressing role in PCa progression via altering the m6A level of a specific RNA population." (PMID 39268470, 2024). "FTO, a key regulator of m6A modifications, exhibits both oncogenic and tumor-suppressive properties across various cancer types." (PMID 39192357, 2024). "In 2018, the endogenous tumour metabolite R‐2HG was reported to competitively inhibit FTO enzyme activity." (PMID 38572667, 2024). "Our results show that most of the genes are negatively correlated with these drugs (based on IC50 values) between high- and low-risk groups in each tumor except for RBFOX2 in some tumors, YTHDF1 in SKCM and LUAD, FTO in LUSC and TGCT, and FMR1 in OV and UCS." (PMID 39457524, 2024). "FTO expression in tumor stage samples was significantly higher in Grade 3 compared with Normal and lower in Grade 1 and Grade 2 compared with Normal." (PMID 38200441, 2024). "Although the role of the FTO gene in the tumor research is still in its early stages, a growing body of evidence suggests that FTO associated with the occurrence and development of a wide variety of tumor and prognosis." (PMID 38166832, 2024). "As given that knockdown FTO enhances the anti-tumor effects of Erastin and RSL3, which targets SLC7A11 and GPX4, respectively." (PMID 38600610, 2024). "This study highlights the pivotal role of FTO in reducing the aggressive growth and enhancing the chemosensitivity of OC cells, establishing it as a key player in the battle against tumor progression and therapeutic resistance." (PMID 39175477, 2024). "Methoxyacetic acid (MA) and its ester derivative MA2, as highly selective FTO inhibitors, significantly inhibit tumor cell growth and self-renewal and slow tumor growth in mouse models, significantly prolonging survival." (PMID 39473440, 2024). "The two quinolone derivatives, identified as FTO inhibitors, were originally investigated for supporting the survival of dopamine neurons in neurodegenerative disease and their anti‐tumour efficacy requires further studies." (PMID 38545841, 2024). "The current study shows that FTO is commonly downregulated in PCa tissues and cell lines and that patients with lower FTO expression have a more advanced tumor stage as well as higher Gleason scores." (PMID 38166703, 2024). "Taken together, these results suggested that FTO downregulation had an inhibitory effect on tumor growth in vivo." (PMID 39692250, 2024). "Dac51 inhibits FTO-mediated tumor cell glycolytic activity, enhancing CD8+ T-cell function and inhibiting solid tumor growth." (PMID 39295872, 2024). "METTL3 and FTO are two of the most extensively studied m6A modifying enzymes during tumor development." (PMID 38711100, 2024). "Currently, METTL3/14 and FTO have emerged as the most extensively reported m6A regulators during tumor development, with a majority of small molecule interventions targeting these two targets." (PMID 38711100, 2024). "Nevertheless, it is crucial to acknowledge that there is no consensus regarding the expression pattern and pathological role of FTO in some tumor types." (PMID 39449798, 2024).
tumor (continued). "At present, the ethyl ester form of meclofenamic acid (MA), as an inhibitor of FTO 27, has been definitely confirmed to prevent tumor growth." (PMID 39132158, 2024). "To verify the effect of FTO in vivo, we injected SiHa‐lv‐shcon or SiHa‐lv‐shFTO cells subcutaneously in nude mice to construct subcutaneous tumor model." (PMID 39692250, 2024). "FTO suppresses the expression of metastasis-associated protein 1 (MTA1) in an m6A-dependent manner, thereby exerting an anti-tumor effect." (PMID 39192357, 2024). "In the research article just cited, FTO-mediated demethylation of m6A in tumor cells upregulated transcription factors c-Jun, JunB, and C/EBPB, thereby allowing cells to rewire their glycolytic metabolism." (PMID 39329974, 2024). "As a result, in CRC, METTL3, METTL14, WTAP, IGF2BP3, YTHDC1, and FTO orchestrate tumor angiogenesis through diverse pathways and mechanisms, thereby affecting the initiation, progression, and prognosis of CRC." (PMID 39295872, 2024). "While the administration of Erastin at 15 mg/kg in FTO knockdown group significantly suppressed the xenograft tumor growth, tumor masses, and Ki67 expression." (PMID 38600610, 2024). "Nevertheless, others have reported the tumour‐suppressive role of FTO,177 emphasising the need for further research before considering clinical studies involving FTO inhibitors in cancer." (PMID 38545841, 2024). "Numerous studies have demonstrated that FTO played a tumor-promoting role in tumorigenesis, but its role in GC development has received less attention." (PMID 38556586, 2024). "Although the roles of FTO in tumor occurrence and development, self-renewal of CSCs, immunity, and metabolism have been extensively explored, its function in tumor angiogenesis is still poorly understood." (PMID 39691597, 2024). "In mice engrafted with glioblastoma stem cells (GSCs), MA2 treatment significantly reduced tumour size, and prolonged survival, suggesting the therapeutic potential of increasing m6A level through FTO inhibition." (PMID 38545841, 2024). "We found that Erastin has a slight inhibitory effect on the tumor growth in FTO knockdown control group." (PMID 38600610, 2024). "To investigate the functional association of the IGF2BP3/MIB1/FTO loop with IGF2BP3-induced NETosis and tumor survival, we disrupted the pathway using a genetic approach." (PMID 38167409, 2024). "In terms of anti-tumor, compound 32 inhibited AML cell proliferation (IC50 = 1.6 ~ 16 μM), induce apoptosis and upregulate ASB2 and RARA, direct targets of FTO, to exert anti-tumor effects." (PMID 38711100, 2024). "The biological functions of the FTO/GAS5/IGF2BP2/QKI axis was assessed using the tumor xenograft assay." (PMID 38782769, 2024). "As a dose-dependent FTO inhibitor, compound 22 can use the hydroxyl and ester groups on the structure to bind into the hydrophobic cavity of FTO to exert anti-tumor activity." (PMID 38711100, 2024). "By inhibiting FTO and increasing the methylation level of transcripts, compound 33 can inhibit the glycolytic capacity of tumor cells and exert antitumor proliferation activity." (PMID 38711100, 2024). "In line with our findings, a previous study also showed decreased expression of FTO in advanced-tumor-stage and high-Gleason-score clinical samples." (PMID 38610981, 2024). "Studies indicate that FTO promotes glycolysis in tumor cells while limiting T-cell immune responses against tumors." (PMID 39192357, 2024). "WNT/β-catenin increases the m6A level of MYC mRNA and promotes its translation by suppressing FTO expression, which promotes tumor cell glycolysis." (PMID 38560499, 2024). "Taken together, these results suggested that targeting FTO by Mupirocin enhances the anti-tumor effects of Erastin or RSL3 in CRC xenografts." (PMID 38600610, 2024).
tumor (continued). "There is strong evidence showing that silencing of FTO can suppress tumor growth, potentiate immune-promoting response, and attenuate drug resistance, thereby highlighting the bright prospect of targeting FTO in cancer treatment." (PMID 38545555, 2024). "Changes in FTO expression can occur under disease conditions, affecting downstream target genes and thereby promoting tumor progression and initiation." (PMID 39192357, 2024). "Since then, mounting evidencing suggested that FTO was a tumor-promoting molecule in many cancers, including GC." (PMID 38556586, 2024). "Similar to CS1 and CS2, Dac51 inhibits tumour growth by promoting T cell infiltration into tumour microenvironment (TME) by inhibiting FTO." (PMID 38943267, 2024). "For instance, FTO, the first known m6A demethyltransferase, is closely related to TME remodeling and tumor escape, and FTO inhibitors exhibit strong antitumor effects in various types of cancer." (PMID 39013954, 2024). "Entacapone and meclofenamate (MA) 2, approved by the U.S. Food and Drug Administration (FDA) as FTO inhibitors, have been demonstrated to hold the efficacy in improving chemotherapy drug sensitivity and inhibiting tumor progression in multiple cancer types." (PMID 38365891, 2024). "To investigate the potential role of FTO in tumor progression, we detected the m6A content in total mRNA with anEpiQuikTM m6A RNA Methylation Quantification Kit (colorimetric) in FTO-overexpressing HEEC and FTO-silenced KYSE150 cells." (PMID 38491196, 2024). "FTO functions as an oncogene in acute myeloid leukemia, promoting malignant transformation and tumor formation." (PMID 38665783, 2024). "A research team reported that, in CRC tissues and cell lines, FTO-mediated regulation of ZNF687 promotes tumor growth, metastasis, and angiogenesis through the Wnt/β-catenin pathway." (PMID 39295872, 2024). "Like ALKBH, FTO also showed conflicting effects, with studies reporting tumor-suppressive effects while others reported oncogenic effects." (PMID 38503745, 2024). "Overall, FTO exerts significant regulatory effects on the proliferation, invasion, apoptosis, oxidative phosphorylation, m6A regulation and downstream tumor-related signaling pathways in AML cells." (PMID 39641872, 2024). "On the other hand, the m6A eraser FTO showed decreased expression in most of the tumor samples compared to the normal tissues." (PMID 38610981, 2024). "Wild-type and FTO knockout PC-3 cells were used to establish an animal xenograft model, and the results showed that FTO knockout PC-3 cells exhibited a substantial increase in tumor development over 35 d of flank xenograft measurement in BALB/c nude mice." (PMID 38384328, 2024). "Specifically within the realm of cancer research, FTO is recognized for its critical role in facilitating tumor progression, promoting invasive behavior, and enabling cellular migration." (PMID 39175477, 2024). "FTO inhibits the self-renewal of ovarian CSCs in vivo, suppressing tumor initiation, both of which require the demethylase activity of FTO." (PMID 39192357, 2024). "In intrahepatic cholangiocarcinoma, FTO disrupts the transcripts of the oncogene TEAD2 in the same way as suppressing tumor progression." (PMID 37007161, 2023). "In another study, FTO was found to be downregulated in Von Hippel-Lindau (VHL)-deficient RCC tissue and correlated with tumour severity and poor prognosis." (PMID 37284313, 2023). "When FTO is knocked down, the expression of angiogenesis inhibitors in tumor tissues is reduced, thus promoting tumor angiogenesis." (PMID 38053093, 2023). "In most cancer types, FTO is upregulated and functions as an oncogene, whereas it also exhibits a tumor-suppressive in certain types of tumors, indicating that FTO function in various cancers is context-dependent." (PMID 37915103, 2023).